RNU4-5P (RNA, U4 small nuclear 5, pseudogene)
Synonyms: U4; U4/6; formerly RNU4P5
Gene: Small nuclear RNA gene on chromosome 10 (109,869,858 to 109,869,992, forward strand). Ensembl gene ENSG00000272160.
Homologues: Orthologues: chimpanzee U4 (97% identical), rat LOC120097636 (64% identical), dog U4 (60% identical), mouse Gm25176 (54% identical), pig U4 (51% identical), rabbit U4 (50% identical). Paralogues in human: RNU4-91P (61% identical), RNU4-6P (57% identical), RNU4-82P (56% identical), RNU4-25P (56% identical), RNU4-4P (56% identical), RNU4-53P (56% identical), RNU4-72P (56% identical), RNU4-81P (56% identical), RNU4-86P (56% identical), RNU4-10P (55% identical), RNU4-18P (55% identical), RNU4-28P (55% identical), and 80 more.